MIF (macrophage migration inhibitory factor)
Diseases named in the same sentence as MIF in open-access papers (continued):
Sharing a sentence is not in itself a finding about the gene and the disease.
acute kidney injury (31 papers, 2012 to 2026). Sudden and sustained deterioration of the kidney function characterized by decreased glomerular filtration rate, increased serum creatinine or oliguria. "There are other studies reported that sCD74/MIF complex was able to enhance the oxidoreductase activity of MIF, thereby protecting the heart and reducing the risk of acute kidney injury induced by oxidative stress after cardiac surgery." (PMID 36712241, 2022). "ROC curve analysis demonstrated a good discriminatory power of 24 h post-OP sCD74 (AUC = 0.83), sCD74/MIF ratio (AUC = 0.82), and D-DT levels (AUC = 0.88) for acute kidney injury, composite outcome, and right heart failure (RHF), respectively." (PMID 42193357, 2026). "In adult cohorts, promoter polymorphisms in the MIF and VEGF genes have been associated with an increased incidence of acute kidney injury and mortality following cardiac surgery." (PMID 40854943, 2025). "An obvious question related to urine MIF is how its levels are influenced by acute kidney injury, which is a common complication in critically ill patients at the ICU58." (PMID 36631486, 2023). "Recently, macrophage migration inhibitory factor (MIF) family protein have received increasing attention owing to its pleiotropic protein molecule character in acute kidney injury, where it performed a dual role in the pathological process." (PMID 36117692, 2022). "Of note, three different murine models of acute kidney injury were used in the Stoppe study and all three models suggested that MIF is protective when there is minimal renal injury." (PMID 35091838, 2022). "MIF exerts a renal protective role by regulating cell apoptosis, promoting cell proliferation and inhibiting fibrosis during the repair process after acute kidney injury." (PMID 36117692, 2022). "Acute kidney injury is divided into different stages based on serum creatinine levels, with the role of MIF in each stage unclear." (PMID 36117692, 2022). "Elevated urinary and plasma MIF levels correlate with acute renal failure, chronic kidney disease, and the polycystic kidney." (PMID 35205271, 2022). "macrophage migration inhibitory factor and macrophage migration inhibitory factor-2 are released into the peripheral circulation when Acute kidney injury occurs and interact with various cellular pathways." (PMID 36117692, 2022). "Stefaniak reported that MIF elevation on the first day after liver transplantation predicts acute kidney injury." (PMID 29120365, 2017). "Inhibition of MIF could also inactivate CD74-NF-κB signaling to protect kidneys against acute kidney injury." (PMID 38052787, 2023). "Furthermore, elevated plasma and urinary MIF levels were found in patients with acute kidney injury compared to healthy controls." (PMID 35091838, 2022). "Likewise, it was found that patients with detectable sCD74/MIF complexes in the serum had a significantly reduced incidence of postoperative acute kidney injury." (PMID 36117692, 2022). "Incidentally, these cells are also the main producers of MIF in acute kidney injury." (PMID 35091838, 2022). "However, when renal injury is more severe like in models of cisplatin or ischemia/reperfusion-induced injury, MIF appears to promote progression of acute kidney injury." (PMID 35091838, 2022). "MIF in plasma and urine is significantly elevated in patients with acute kidney injury (AKI) and elevated MIF in serum is associated with markers of oxidative stress, endothelial dysfunction, arterial stiffness, and markers of myocardial damage in chronic kidney disease (CKD)." (PMID 26858715, 2016). "MIF levels have been shown to correlate with disease severity and therefore the release of MIF in more severe acute kidney injury maybe significantly higher than in mild acute kidney injury." (PMID 35091838, 2022).
acute kidney injury (continued). "Interestingly, treatment of MIF knockout mice with D-DT significantly ameliorated tubular injury suggesting that MIF and D-DT may have similar roles in ischemia/reperfusion-induced acute kidney injury." (PMID 35091838, 2022). "Given that tubular injury and (programmed) cell death are hallmarks of acute kidney injury (AKI), and tubular cell regeneration is an essential process in healing, the role of MIF was also analyzed in this setting." (PMID 35096904, 2021). "It was also possible that MIF may mediate acute kidney injury via CD74/TLR4-NF-κB signaling." (PMID 32964038, 2020). "This article therefore aims at reviewing available data on the role of MIF in acute kidney injury (AKI), CKD, diabetic nephropathy, inflammatory kidney disease, and genetic aspects of MIF and kidney disease." (PMID 26858715, 2016). "Furthermore, MIF seems to be involved in vascular processes and cardiovascular disease associated with CKD, glomerulonephritis, autosomal dominant polycystic kidney disease, and possibly also in progression to renal failure." (PMID 26858715, 2016). "A few years later, they further confirmed the protective effects of RPS19 treatment in a mouse model of cisplatin-induced acute kidney injury, showing downregulation of MIF/CD74-induced inflammation, which was similar to results found with MIF knock-out mice." (PMID 35091838, 2022). "Therefore, MIF may have opposite effects based on the time and severity of acute kidney injury." (PMID 35091838, 2022). "The specific role and mechanism pathways of MIF, its structural homologue MIF-2 and surface receptor CD74 in the progression of acute kidney injury needs to be investigated deeply, especially the related research of MIF-2 is still relatively few." (PMID 36117692, 2022). "In addition, the rate of acute kidney injury (AKI) was dramatically reduced in cardiac surgery patients with high circulating MIF at 12 h postoperatively." (PMID 34540864, 2021). "A study has prompted new clues that show the role of MIF in AKI, indicating elevated urine MIF levels in patients were accompanied by the occurrence of AKI and urine MIF can be used as a potential biomarker of acute kidney injury in patients with acute pyelonephritis." (PMID 36117692, 2022). "The peak value of MIF release is negatively related to post-operative atrial fibrillation and acute kidney injury, whereas the level of MIF2 is opposite of MIF and intraoperative MIF2 levels are related to the increased incidence of post-operative atrial fibrillation and pneumonia." (PMID 36712241, 2022). "The frequency of high-producer MIF -173 G/C genotype was higher (10.1%) in ESRD than in controls (1.2%), suggesting that it may play a role in progression to renal failure." (PMID 26858715, 2016). "During ICU treatment, patients undergoing CRRT due to septic acute kidney injury showed lower MIF levels compared to septic patients without the need for CRRT." (PMID 27313864, 2016). "This study reveals a potential role of MIF in acute kidney injury (AKI) in patients and in kidney ischemic reperfusion injury (IRI) mouse model in MIF wild‐type (WT) and MIF knockout (KO) mice." (PMID 30968541, 2019). "The effect of continuous renal replacement therapy (CRRT) on daily MIF levels and mortality was assessed by comparing patients with and without need for CRRT due to acute kidney injury (AKI)." (PMID 27313864, 2016). "Macrophage migration inhibitory factor (MIF) is a proinflammatory cytokine, and the predictive role and pathogenic mechanism of MIF deregulation during kidney infections involving acute kidney injury (AKI) are not currently known." (PMID 23319831, 2012). "In addition, MIF20 exerts a myocardial protective effect via MIF-AMPK pathway and subsequent myocardial glucose uptake in the ischemic myocardial injury model, however, its role has not been reported in acute kidney injury." (PMID 36117692, 2022).
neuroblastoma (29 papers, 2013 to 2025). Neuroblastoma (NB) is the most common solid, extracranial childhood tumor. "Next to these tumor-intrinsic effects, we found that tumor-secreted MIF is associated with reduced cytotoxicity of tumor-infiltrating lymphocytes in neuroblastoma." (PMID 39908652, 2025). "In the present study, we have identified macrophage migration inhibitory factor (MIF) as a key inflammatory cytokine potentially involved in Bone Marrow (BM) infiltration in patients with high-risk neuroblastoma (NB)." (PMID 35715791, 2022). "As prognostic markers, MIF and its associated receptors play a significant role in neuroblastoma." (PMID 41159021, 2025). "Since CAR T-cell therapy is a promising upcoming treatment strategy for neuroblastoma, we investigated the suppressive effect of MIF and MDK on T cells specifically." (PMID 39908652, 2025). "Taken together, these studies suggest an important intrinsic role for MIF in neuroblastoma growth and progression, which makes MIF a particularly attractive target for therapeutic intervention." (PMID 39908652, 2025). "MIF was found in all 21 neuroblastoma samples studied, with both MIF and c-Met (tumor progression related receptors) detected in the cytoplasm of tumor cells." (PMID 41159021, 2025). "To evaluate the effect of MIF on tumor cell killing by GPC2 CAR-T cells, we quantified CAR-T cell killing capacity against MIF-deficient neuroblastoma cells (SK-N-BE2C-shMIF) in co-cultures." (PMID 39908652, 2025). "More recently, MIF has been described in several malignancies, including neuroblastoma, to correlate with tumor growth, metastases and survival." (PMID 39908652, 2025). "Here, we used a multi-omics approach to pinpoint immunosuppressive factors hampering CAR-T efficacy, which identified MIF as a neuroblastoma-derived, abundantly secreted, immunosuppressive factor." (PMID 39908652, 2025). "In in vitro studies and nude mice models, downregulation of MIF significantly reduced neuroblastoma cell proliferation, tumor formation, and metastasis." (PMID 41159021, 2025). "Taken together, MIF PROTAC treatment provides a promising therapeutic strategy to reduce MIF secretion by neuroblastoma tumors and thereby enhance activation of clinically relevant CAR T-cells." (PMID 39908652, 2025). "Degradation of MIF by PROTAC treatment enhanced the efficacy of multiple neuroblastoma-targeting CAR T-cells, which provides a novel therapeutic strategy to enhance CAR-T cell efficacy in patients with neuroblastoma." (PMID 39908652, 2025). "We observed that neuroblastoma tumor cells express high levels of MIF and partially depend on MIF for their proliferation and/or survival, which is consistent with prior findings." (PMID 39908652, 2025). "Where MIF likely promotes neuroblastoma development by regulating N-Myc and increasing the expression of angiogenic factors." (PMID 41159021, 2025). "Double immunohistochemistry staining demonstrated that neuroblastoma cells highly expressed MIF and c-Met, with a strong positive correlation between their expressions." (PMID 41159021, 2025). "Transfection of miR-451 mimics into SK-N-SH and GI-LA-N neuroblastoma cells reduced MIF protein levels, as confirmed by Western blot analysis." (PMID 41159021, 2025). "A knockdown of TGFβ1 in neuroblastoma cells decreased the levels of L1-70 and the pro-inflammatory cytokine macrophage migration inhibitory factor (MIF)." (PMID 38542077, 2024). "Treatment of mouse neuroblastoma N2a cells with the L1 agonist tacrine led to enhanced levels of full-length L1, L1-70 and macrophage migration inhibitory factor." (PMID 36768419, 2023). "In order to further investigate the relationship between circulating TGFβ-1, L1-70, and MIF expression, mouse neuroblastoma N2a cells were transfected with TGFβ-1 siRNA." (PMID 35013124, 2022). "MIF has been reported to inhibit apoptosis in myocardium, cervical cancer cells, neuroblastoma cells, and multiple myeloma cells." (PMID 36147562, 2022).
neuroblastoma (continued). "We found that TGFβ-1, L1-70, and MIF were increased in the serum of old AD mice at 3 days after parabiosis surgery, and knock down of TGFβ-1 with siRNA in neuroblastoma cells decreased L1-70 and MIF expression along with the decrease in TGFβ-1." (PMID 35013124, 2022). "MIF expression is upregulated in many CNS diseases such as Alzheimer's, cerebral ischemia/reperfusion, neuroblastoma, and traumatic brain injury." (PMID 32964038, 2020). "An in vitro study using an MIF inhibitor in the neuroblastoma cell line revealed amelioration of the neurotoxic effect of MIF and Aβ protein production." (PMID 32116650, 2020). "Neuroblastoma has decreased expression of miR-451, which inhibits macrophage migration inhibitory factor (MIF), resulting in increased macrophage infiltration." (PMID 28536380, 2016). "By studying AS-MIF-transfected cells, researchers have gained insights into how MIF blockade may affect the expression of molecules related to neuroblastoma." (PMID 41159021, 2025). "Intriguingly, MIF depletion alone reduced the baseline growth rate of the tumors, possibly indicating an intrinsic dependency of neuroblastoma cells on MIF for proliferation and survival, which renders MIF a particularly promising target for therapeutic intervention." (PMID 39908652, 2025). "Indeed, treatment with MD13 reduced the concentration of secreted MIF in the culture supernatant of neuroblastoma tumoroids, with a maximal reduction of 81–84 % after 48 h." (PMID 39908652, 2025). "In neuroblastoma, MIF mediates the suppression of macrophage migration and T‐cell responses." (PMID 39834330, 2025). "MIF also plays a role in drug resistance in acute myeloid leukemia and neuroblastoma cells." (PMID 40880391, 2025). "MIF upregulation in neuroblastoma can induce MYCN expression, resulting in tumor progression." (PMID 39908652, 2025). "Targeting MIF may therefore be a viable strategy to increase the efficacy of CAR T-cell therapy for patients with neuroblastoma." (PMID 39908652, 2025). "•Knock-out of MIF in neuroblastoma increased CAR-T cell efficacy in vitro and vivo." (PMID 39908652, 2025). "However, transfection of SK-N-DZ neuroblastoma cells with an AS-MIF expression vector reduced MIF expression, leading to a decrease in pro-tumor genes such as N-Myc, TrkB, Ras, and IL-8, while tumor-suppressing genes like EPHB6 and BLU were elevated." (PMID 41159021, 2025). "Similarly, neuroblastoma cells secreting MIF inhibit T cell proliferation and induce cell death through an IFN-γ pathway, which eliminates activated T cells from TME, thus contributing to tumor cell escape from immune surveillance." (PMID 35842634, 2022). "Moreover, recombinant MIF administration is effective for inducing the expression of brain-derived neurotrophic factor and promotes neuroprotection of neuronal cells in human neuroblastoma cell lines under oxygen-glucose deprivation." (PMID 35324982, 2022). "However, a significant increase in MIF with a significant concurrent loss of COX-2 activity was only found in cancers of nervous systems and brain (e.g., ependymoma and neuroblastoma)." (PMID 29247872, 2017). "Of note, the MIF/CXCR4 signaling axis has been implicated in the survival, invasion, and drug resistance of patient-derived neuroblastoma cells in the bone marrow microenvironment and may provide an explanation for the high propensity of bone metastasis in neuroblastoma." (PMID 38732068, 2024). "In an earlier study by Zhou and co-workers, production of high amounts of MIF by neuroblastomas (NB) led to a decrease in the number and infiltration of CD8+ and CD4+ T cells, and ultimately, suppression of antitumor immunity." (PMID 35842634, 2022). "Therefore, we may envisage the possibibility to use nitric oxide (NO)-hybridized drugs, such as NO-aspirin or NO-hybridized antiretroviral protease inhibitors, such as lopinavir-NO, for the treatment of MIF-dependent disorders including, neuroblastoma." (PMID 31635049, 2019).
neuroblastoma (continued). "Analysis of public gene expression datasets revealed that both MIF and CXCR4 were highly expressed in primary neuroblastoma tumors and BM-derived disseminated neuroblastoma tumor cells." (PMID 41159021, 2025). "ScRNA-seq revealed 13 immunosuppressive interactions in the TME of neuroblastoma, two effectors of which, Midkine (MDK) and Macrophage Migration Inhibitory Factor (MIF), were validated as candidate targets across multiple published datasets." (PMID 39908652, 2025). "To validate the potential roles of MIF and MDK in neuroblastoma, we confirmed their protein expression by mass-spectrometry of 11 neuroblastoma tumoroids." (PMID 39908652, 2025). "Taken together, these data indicate potential immunosuppressive roles of MIF and MDK in the neuroblastoma TME." (PMID 39908652, 2025). "To investigate the roles of MIF and MDK on CAR T-cell modulation, we used CAR T-cells targeting GPC2, which have shown robust safety and efficacy in diverse preclinical models of neuroblastoma and are currently being tested clinically (NCT05650749)." (PMID 39908652, 2025). "To study this interaction, we generated neuroblastoma cell lines with genetic depletion of MDK (SK-N-AS-shMDK and SH-SY5Y-shMDK) or MIF (SK-N-BE2C-shMIF and Kelly-shMIF) using shRNA-mediated silencing." (PMID 39908652, 2025). "MIF administration protected neurons from hypoxic injury by upregulation of mature BDNF and anti-apoptotic molecules in human neuroblastoma cells." (PMID 38178143, 2024). "We have also shown that the inhibition of the expression of both MIF and DDT, by short interfering RNA, in vincristine-resistant NKF-NB-3 neuroblastoma cells, is able to revert drug resistance." (PMID 31635049, 2019). "We therefore specifically quantified MIF and MDK secretion by neuroblastoma tumoroids." (PMID 39908652, 2025). "•Multi-omics identified MIF and MDK as immunosuppressive targets in neuroblastoma." (PMID 39908652, 2025). "Compared to healthy tissues, both MIF and MDK were overexpressed in neuroblastoma." (PMID 39908652, 2025). "By defining the immunosuppressive effects of neuroblastoma’s TME on CAR T-cell efficacy, revealing the pivotal role of MIF, we provide an analytic pipeline and therapeutic strategy for improving adoptive cell therapies for this pediatric malignancy and potentially other solid tumors." (PMID 39908652, 2025). "Unraveling the involvement of MIF and MDK in neuroblastoma metastasis could provide important information in the future." (PMID 38087370, 2023). "However, recently it was described that macrophage migration inhibitory factor (MIF) and midkine (MDK) are expressed in neuroblastoma, factors that are known to be involved in metastasis in other cancers." (PMID 38087370, 2023). "Finally, another study was performed to test in vitro if increased synthesis of MIF can prevent the accumulation of misfolded SOD1 and protect against its toxicity in the SH-SY5Y neuroblastoma cell line." (PMID 32344747, 2020). "In particular, in in vitro studies, MIF chaperone activity inhibits the formation and toxicity of misfolded SOD1 amyloid aggregates, when overexpressed in neuroblastoma cell lines such as SH-SY5Y or mouse motor neuron-like hybrid cell line NSC-34 differentiable in motor neurons." (PMID 32344747, 2020). "Given the broad expression of MIF across solid tumors, inhibition or degradation of MIF may be a viable strategy to improve CAR T-cell efficacy not only in neuroblastoma but in many solid cancers." (PMID 39908652, 2025). "In addition, high MIF and MDK expression was significantly associated with inferior event-free and overall survival of neuroblastoma patients, which was independent of MYCN amplification." (PMID 39908652, 2025). "MIF overexpression is considered a negative prognostic factor in neuroblastoma." (PMID 32964038, 2020). "Interestingly, neuroblastomas, which are of NCC origin, express high level of MIF." (PMID 32318567, 2020).
neuroblastoma (continued). "Transcriptomic analyses have identified MIF and DDT as negative prognostic factors in patients with neuroblastoma, regardless of MYCN amplification." (PMID 38732068, 2024).